COL4A3 (collagen type IV alpha 3 chain)
Diseases named in the same sentence as COL4A3 in open-access papers (continued):
Sharing a sentence is not in itself a finding about the gene and the disease.
kidney disease (continued). "For instance, Col4a3 knockout mice on the 129/Sv background typically develop end-stage renal disease more rapidly than Col4a5 G5X mice on the C57BL/6.Cg background." (PMID 41290692, 2025). "In view of this very low percentage of patients with P/LP variants in the COL4A3/COL4A4 genes with cystic nephromegaly, it seems advisable to exclude other inherited kidney diseases when cystic nephromegaly is present." (PMID 38317457, 2024). "As one of the components that constitute the glomerular BM, defects in COL4A3 can lead to inherited renal diseases." (PMID 37841281, 2023). "In this study of 42 individuals with a variant in one of the alleles of the COL4A3/COL4A4 gene from 17 Dutch families, we investigated kidney disease symptoms and kidney biopsies." (PMID 36925663, 2023). "Five unclassified COL4A3/COL4A4 variants, which were detected in five of 343 patients with hereditary kidney diseases, were analysed." (PMID 35386907, 2022). "Previous studies comparing Col4a3-/- 129J with C57Bl/6 strain showed that genetic background can influence renal disease progression, consistent with variations seen in human AS pedigrees." (PMID 35743114, 2022). "Vimentin levels increase in Col4a3-/- mice by 5 weeks, and in other renal diseases, but the significance of these changes in expression with disease is not clear." (PMID 27942003, 2016). "Five genes (PKD1, PKD2, and COL4A3/A4/A5) accounted for the majority of diagnoses in both our cohort and others, suggesting that focusing on these common genes can capture most hereditary kidney disease cases." (PMID 40533884, 2026). "Mono-allelic variants in COL4A3 were identified in 5 index patients and in COL4A4 in 12 index patients.26, 27, 28, 29, 30, 31 All index patients had a positive family history of kidney disease." (PMID 36925663, 2023). "Here, we describe in-depth clinical, pathological, and genetic investigations of 42 patients from 17 families with 8 different mono-allelic variants in COL4A3 or COL4A4, identified with a kidney disorders gene panel using whole exome sequencing in a diagnostic approach." (PMID 36925663, 2023). "Double knockouts of COL4A3 and either DDR1 or integrin α2 show attenuated kidney disease progression, implicating these receptors as contributors to the pathobiology of Alport glomerular disease." (PMID 35223933, 2022). "Given that heterozygous COL4A3/COL4A4 mutations were observed in patients with familial FSGS 2, 4, and FSGS can be secondary to TBMN and AS 36, 37, 38, FSGS may be only a pathological lesion process in the related kidney diseases or secondary to the GBM pathology." (PMID 27469977, 2016). "Predicted pathogenic variants of the COL4A5 gene were established in one out of 2320 individuals, and COL4A3 and COL4A4 variants in one in 106 individuals in populations without kidney disease." (PMID 36982595, 2023). "Previous work showed that double knockouts of COL4A3 and either DDR1 or integrin α2β1 resulted in attenuated kidney disease progression in the autosomal Alport mouse model, clearly implicating aberrant DDR1 and/or α2β1 signaling in Alport glomerular pathogenesis." (PMID 35223933, 2022). "Predicted pathogenic heterozygous COL4A3 and COL4A4 variants affected one in 106 individuals, consistent with the finding of TBMN in kidney biopsies in donors without known kidney disease." (PMID 35547199, 2022). "In the patient with typical extrarenal features and GBM lamellation (index of family 11), whole exome sequencing using a kidney disorders gene panel identified COL4A4 variant c.2690G>A (p.Gly897Glu), but no additional variants in COL4A3/COL4A4/COL4A5 or other podocyte-related genes." (PMID 36925663, 2023). "When COL4A3/4/5 gene testing and subsequent analysis of the larger panels of genes involved in (glomerular) kidney diseases are negative, the possibility of deep-intronic, regulatory, and structural variants such as inversions that might have been overlooked should be considered." (PMID 39673454, 2025).
tumor (20 papers, 2012 to 2025). "The COX proportional hazard model demonstrated that doubled expressions of three genes, i.e., CREB5, PTPRB and COL4A3, was associated with 63% to 97% decreased risk of death, recurrence or progression, suggesting their potential role as tumor suppressors." (PMID 25105010, 2014). "The COL4A1 and COL4A2 had the most significant association with tumor grade (AUC = 0.822 and 0.820 in G2 vs G3 and G4; AUC = 0.863 and 0.834 in G3 vs G4), followed by COL4A3 and COL4A4 (AUC = 0.539 and 0.585 in G2 vs G3 and G4; AUC = 0.677 and 0.753 in G3 vs G4)." (PMID 40351420, 2025). "In addition, expression of COL4A3 was associated with tumor size, higher grade, metastasis, and invasion in several malignancies." (PMID 33540941, 2021). "COL4A3/4 was negatively correlated with tumor purity while positively correlated with CD8 + T cells, B cells, dendritic cells, macrophages, neutrophils, and CD4 + T cell infiltration." (PMID 38907304, 2024). "Overexpression of COL4A3 has been correlated with tumor size, higher grade, metastasis, and invasion in several malignancies." (PMID 35956764, 2022). "The participation of stimulated MSCs in tumor matrix remodeling was also supported by the increase of COL4A3 gene." (PMID 25797265, 2015). "Reverse transcription-quantitative polymerase chain reaction validation results demonstrated that KRT8 and S100A16 were significantly upregulated in tumor tissues, while COL4A3 and SMAD9 expression was downregulated, which was consistent with the TCGA-LUAD database analysis." (PMID 41239716, 2025). "Moreover, gene expression analysis showed that the expressions of KRT8 and S100A16 were significantly increased in tumor tissues, while the expressions of COL4A3, SMAD9, MAP3K8 and CCDC146 were decreased." (PMID 41239716, 2025). "We found that CSC-derived EVs promoted persistent phenotypical changes in MSCs characterized by an increased expression of genes associated with cell migration (CXCR4, CXCR7), matrix remodeling (COL4A3), angiogenesis and tumor growth (IL-8, Osteopontin and Myeloperoxidase)." (PMID 25797265, 2015). "Therefore, the increased vessel formation in tumors may be associated with the upregulation of COL4A1 and COL4A2 expression, and the aggressiveness of the tumor may result in the downregulation of COL4A3 and COL4A4 expression and minor Col IV degradation to promote invasion of tumors." (PMID 40351420, 2025). "As the tumor progressed, COL4A1, COL4A2 and COL4A6 expression gradually increased, and COL4A3, COL4A4 and COL4A5 gradually decreased." (PMID 40351420, 2025). "DMA identified 59,654 differential methylation sites between two clusters and part of these sites were correlated with tumor angiogenesis genes including CDH13, COL4A3, and RHOB." (PMID 33761933, 2021). "COL4A3 has suppressed expression in COPD, and is tied by the CLR algorithm to the transcription factors PML (also a tumor suppressor) and PITX2." (PMID 22829758, 2012). "Furthermore, eight target genes (COL4A3, FAM30A, FCRL5, MDM4, SYNE2, TNFRSF13C, TPTEP2, VAMP1) were systematically positively correlated with ESR2 expression patterns in tumor types with low ESR2 expression as a prognostic factor concerning OS or DFS." (PMID 39201394, 2024). "The fact that Collagen signatures exhibit strong predictive power may be because these members themselves (COL1A1, COL4A3, COL5A1, COL11A1, COL22A1) have been reported to predict tumor prognosis." (PMID 37476379, 2023). "From feature analysis we concluded that collagens, MACROH2A1, HPF1, COL4A3, TBB2C, actin, and H2B are promising targets for the understanding of tumor progression and development of distant metastases, and consequently inspiring novel treatment of PDAC metastatic lesions." (PMID 35956764, 2022).
tumor (continued). "The mRNA expression level of all six type IV collagen genes (COL4A1, COL4A2 COL4A3, COL4A4, COL4A5 and COL4A6) was higher in metastatic tissue compared to primary tumor tissue, although being significant only for COL4A3 (p = 0.013) and COLA4A4 (p = 0.005) genes." (PMID 35693557, 2022). "For example, we found that the COL4A3 annotated in the ECM-receptor interaction pathway was both hypomethylated and up-regulated in metastasis tissues, which might play a role in tumour metastasis." (PMID 27109211, 2016). "In contrast, the variation of COL4A3, COL4A4 and COL4A5 expression between tumor and normal tissues were lacking of significance, and presented an inconsistent tendency in three databases." (PMID 40351420, 2025). "On the other hand, Col4a1, Col4a3, Col4a5, Col5a3, Col11a2, Col14a1, Col15a1, Col16a1, and Col22a1 were found in normal ECM but not in tumor ECM; Col25a1 was found only in tumor ECM but not in normal ECM." (PMID 36547361, 2022).
cancer (10 papers, 2017 to 2025). A tumor composed of atypical neoplastic, often pleomorphic cells that invade other tissues. "The only unequivocal “anti-cancer” cases are DPP6 in ESCA (for AP-2α) or COL4A3 in UCEC (for AP-2γ) but this cannot be concluded only on the basis of the single TF–target example." (PMID 35361846, 2022). "Additionally, genes like ACTA1, COL4A3, A2M, ADRB2, MYOC, among others, are closely associated with cancer biomarkers, candidate prognostic factors, and therapeutic targets." (PMID 39968416, 2025). "The prognostic outcome of COL4A3 could also vary depending on cancer type." (PMID 35361846, 2022). "Subgroup-specific genes with strong effects on overall survival and high MIFs in the proposed weighted model involve the following cancer-related genes: ADH1C, BMP5, LCN2 and PLOD2 in GSE31210, CST1 in GSE37745, as well as AREG and COL4A3 in GSE29013." (PMID 34876106, 2021). "Hence, AAb against COL4A3 may worsen the state of cancer by preventing the generation of tumstatin." (PMID 29062084, 2017). "For example, genes related to significantly enriched GO terms of cell adhesion and apoptosis, included COL4A3, PHLPP1, and TIA1, which were reportedly downregulated in cancer." (PMID 28903418, 2017).
genetic disorder (6 papers, 2018 to 2025). "AS is a rare genetic disorder that caused by pathogenic variants in COL4A3, COL4A4, and COL4A5 that result in abnormalities of the collagen IV α345 network of basement membranes." (PMID 34774011, 2021). "Studies have shown that 15–60% of human genetic diseases are caused by splicing variants, and it has been speculated that the true proportion of splicing variants in COL4A3/COL4A4 may be underestimated." (PMID 35386907, 2022).
infection (2 papers, 2022 to 2024). The state of being infected such as from the introduction of a foreign agent such as serum, vaccine, antigenic substance or organism. "Inflammation- and infection-associated genes TIMP2 (tissue inhibitor of metalloproteinase 2) (rs2277698), COL4A3 (collagen type IV alpha 3 chain) (rs1882435) and TNF variants were explored in more than one targeted study." (PMID 35379367, 2022). "Wnt signaling molecules, genes associated with inflammation and infection, such as EBF1, TIMP2, COL4A3, TNF, and the candidate gene for schizophrenia, i.e., ABCA13, have been identified as PTB biomarkers through the multiple target studies, though their mechanisms remain unclear." (PMID 38391647, 2024).
kidney (2 papers, 2014 to 2020). "MMF reversed the COL4A3 related phosphorylation status of renal proteins in this murine fibrotic kidney model to that seen in WT mice." (PMID 25525413, 2014).
autosomal dominant disease (1 paper, 2025). Autosomal dominant form of disease. "It must also be acknowledged that study participants with autosomal dominant disease represented a severe disease subset of the larger group of participants with heterozygous variants in COL4A3 and COL4A4." (PMID 40485716, 2025).
cardiac diseases (1 paper, 2022). "However, cardiac diseases were independent of the functions of LAMC1, COL4A3, and ATP2C2." (PMID 35924220, 2022).
cardiovascular disease (1 paper, 2022). "In conclusion, our results confirm major roles for genetic background on AS progression in mouse models as they relate to cardiovascular disease, cardiorespiratory functions, blood pressure and renal tubular SGLT2 expression in male and female Col4a3-/- mice." (PMID 35743114, 2022).
inflammation (1 paper, 2023). Aberrant reaction of the microcirculation characterized by movement of fluid and leukocytes from the blood into extravascular tissues. "Unfortunately, both the Col4a3−/− and adenine-induced CKD mice used in this study are too sick to introduce accompanying acute or chronic lung inflammation." (PMID 36966182, 2023).
COL4A3 also shares sentences with these, for which no sentence is quoted: autosomal dominant Alport syndrome (20 papers); autosomal recessive Alport syndrome (18); X-linked Alport syndrome (10); glomerulopathy (9); Hematuria (7); autoimmune disease (3); nail-patella syndrome (3); nephritis (3); HIV-associated nephropathy (2); lupus nephritis (2); Pierson syndrome (2); polycystic kidney disease (2); Renal cyst (2); anemia (1); aneurysm (1); aniridia (1); Apert syndrome (1); atypical hemolytic-uremic syndrome (1); autosomal recessive polycystic kidney disease (1); autosomal-dominant tubulointerstitial kidney disease (1); bladder cancer (1); cataract (1); ciliopathy (1); Cognitive impairment (1); colorectal cancer (1); congenital nephrotic syndrome (1); corneal endothelial dystrophy (1); Dent disease (1); Denys-Drash syndrome (1); dilated cardiomyopathy (1).
A further 55 diseases each share a sentence with COL4A3 in 1 paper.